APOE (apolipoprotein E)
Diseases named in the same sentence as APOE in open-access papers (continued):
Sharing a sentence is not in itself a finding about the gene and the disease.
amyloid (continued). "Notably, genetically decreasing apoE expression results in less Aβ deposition in amyloid mouse models, independently of apoE isoform." (PMID 31186040, 2019). "Human apolipoprotein E found in three isoforms (E2; E3; E4) is a member of a family of apolipoproteins that under pathological conditions are detected in extracellular amyloid depositions in several amyloidoses." (PMID 31071995, 2019). "However, subsequent work by the same group showed that knocking out both CLU and APOE in PDAPP mice resulted in increased Aβ production and amyloid deposition and earlier onset of AD-pathology than the APOE-KO alone." (PMID 30872998, 2019). "APOE has long been known for its role in modulating AD and CAA risk (depending on the combination of the three human isoforms APOE2, APOE3 and APOE4) and for its ability to bind Aβ peptides and to be recruited to amyloid deposits." (PMID 31798396, 2019). "Interestingly, plasma concentrations of ApoE significantly increased in the amyloidosis-induced groups compared with the Con group in the present study." (PMID 31281565, 2019). "Apolipoprotein E (APOE) genotype, the most widely shared genetic risk factor for late-onset AD, is a strong candidate regulator of TREM2-dependent microglial interactions with amyloid plaques." (PMID 31113487, 2019). "Moreover, the posterior nodes of DMN have received great attention showing significant modification in normal aging and moreover in AD, indicating amyloid deposition and reduction of metabolism, also in preclinical conditions as observed in APOE E4 patients." (PMID 29568755, 2018). "Since many amyloid-related proteins including SAA, ApoA-I, ApoA-IV, ApoC-II, ApoE, clusterin, and Aβ are associated with HDL, nutritional treatments modifying the metabolism of HDL might prevent several types of amyloidosis." (PMID 28225824, 2017). "The main mechanism in amyloid pathology in fAD is the increased production of Aβ species, whereas decreased Aβ clearance is postulated in sAD, which is modulated by the apolipoprotein E (APOE) genotype." (PMID 29191219, 2017). "The other 5 APOE ε4 allele bearers not showing amyloid plaque formation were all under 65 years of age at death." (PMID 27036121, 2016). "The prevalence of PET amyloid-positivity is 98% in ApoE ɛ 4/4-positive AD patients." (PMID 27891223, 2016). "Additionally, inducing Abca1 using either pharmacological or genetic methods can improve cognitive function and reduce amyloid levels in AD mouse models and increase apoE lipidation in the brain." (PMID 27598782, 2016). "Since Aβ levels and APOE ɛ4 status have been shown to be associated with the increase in the size of early endosomes observed in neurons from AD patients, we analysed the potential correlation between amyloid burden, the APOE status and the mean endosomal volumes in the AD groups." (PMID 26151923, 2015). "Our results suggest that the relationship between neuronal lipid biology and neurodegeneration may be influenced by amyloid pathology even after controlling for the effects of APOE ε4." (PMID 24088526, 2013). "However, aducanumab was linked to amyloid-related imaging abnormalities (ARIA), specifically vasogenic edema (ARIA-E), occurring in a dose-dependent manner in 3–41% of recipients, especially in carriers of the APOE ε4 allele." (PMID 39996737, 2025). "Interestingly, in our here presented 3D human amyloidosis model we only detected APOE-Aβ interaction if hiMG were present during the Aβ treatment, particularly 5w and to a lesser extend after 3w long exposure, mimicking the colocalization found in the AD brain." (PMID 40275379, 2025). "Thenon-APOE amyloid GRS was also associated with hallmarkpostmortem neuropathologic features of AD (β-amyloid plaque andneurofibrillary tangle pathology) and in an independent validation sample wasassociated with plasma p-tau181 concentrations (a robust indicator ofcerebral amyloidosis)." (PMID 40703204, 2025).
amyloid (continued). "Notably, whereas CSF apoE levels did not appear to be affected by the APOE genotype or AD diagnosis, some studies suggest that amyloidosis is associated with reduced CSF apoE levels in an APOE4 genotype-dependent manner." (PMID 36153580, 2022). "To evaluate the applicability of this method in the study of amyloid genesis, we also investigated associated proteins that are frequently observed in amyloid deposition, such as serum amyloid P (SAP), apolipoprotein A4 (Apo A4), apolipoprotein E (Apo E), and vitronectin (VTN)." (PMID 36240260, 2022). "Thus, it remains unclear whether peripherally-derived apoE (or lack thereof) exerts any effect on cerebral amyloid pathology when apoE is still present in the brain." (PMID 31623648, 2019). "Thus, we investigated whether apoE can be found in microglia in the setting of amyloidosis, specifically in the APP/PS1–21 model which develops Aβ deposition in amyloid plaques beginning at 6–8 weeks of age." (PMID 31623648, 2019). "In addition, in the presence of abundant amyloidosis, APOE ɛ4 may have accelerated entorhinal cortex tau deposition." (PMID 31642932, 2019). "We found this virtual absence of apoE in the plasma to cause significant alterations in the plasma lipid profile without significantly altering cerebral amyloid plaque accumulation in a model of Aβ-driven amyloidosis." (PMID 31623648, 2019). "Since the Apolipoprotein E (APOE) ε4 allele, a genetic risk factor for sporadic AD, is associated with amyloid pathology and functional and structural brain changes in cognitively normal subjects we also examined whether APOE ε4 modified the relationship between amyloid and gray matter networks." (PMID 29599717, 2018). "The difference of amyloid plaque burden between ApoE ɛ 4 carriers and ApoE ɛ 4 non carriers patients, may be explained that Aβ deposition starts earlier and continues for a longer time in ApoE ɛ 4 carriers." (PMID 27891223, 2016). "Taken together with these recent findings, our results suggest that LXR agonists not only increased apoE synthesis and lipidation, but also led to reduced levels of apoE receptors in the brain, which could result in further improvement of apoE-bound amyloid clearance from the CNS." (PMID 21034469, 2010). "ASPs consisting of APOE, SAP, and APOA4 have been reported to be excellent surrogates for diagnosing amyloidosis when at least two were detected by LC-MS/MS." (PMID 41571866, 2026). "In the SMC-calc vs. SMC comparison based on limma, clusters related to high-density lipoprotein (HDL) assembly (PF4V1, APOA1, LPXN, AFP, A2M, and MMP1) and amyloidosis (CX3CL1, APOE, PLIN3, TGFBI, and CH25H) were identified." (PMID 41301179, 2025). "Knock-down of APOE mRNA with oligonucleotide (siRNA and ASO) approaches are tractable using current technology and have proved successful when tested in both tau and amyloid mouse models." (PMID 40770764, 2025). "Proteins such as clusterin, vitronectin, apolipoprotein E (ApoE), ApoA4, and serum amyloid P-component (SAP) constitute amyloid signature proteins found in all types of amyloidosis and across all affected tissues." (PMID 38892061, 2024). "To further evaluate the possible effects of amyloid status on TSPO-binding in different APOE ε4 gene doses, we analyzed also the interaction of Aβ-positivity × APOE ε4 gene dose for predicting regional TSPO-binding." (PMID 37016464, 2023). "Third, amyloid PET is unable to distinguish between amyloid plaques relevant to AD and amyloid buildup in arteries indicative of cerebral amyloid angiopathy (CAA), and there are known APOE genotype differences in CAA." (PMID 36597122, 2023).
amyloid (continued). "APOE4 is involved in amyloid production, formation of amyloid plaques and APOE/amyloid complexes, cellular clearance of amyloid, amyloid clearance through the blood-brain barrier, and proteolytic degradation." (PMID 36597122, 2023). "We utilized APOE knock-in mice capable of having APOE selectively removed from astrocytes in a tamoxifen-inducible manner and crossed them with the APP/PS1-21 mouse model of amyloidosis." (PMID 35109920, 2022). "Taken together, our findings suggest that the interaction between ApoE and ADan plays a key role in FDD pathogenesis, in addition to the known role for ApoE in amyloid plaque formation in AD." (PMID 36436561, 2022). "As far as we know, three proteins named apolipoprotein E (APOE), apolipoprotein A-IV (APOA4), and serum amyloid P component (SAP) are usually accompanied with amyloid deposition in amyloidosis." (PMID 35418036, 2022). "This method also provides the identification of common amyloidosis marker proteins such as SAP and apolipoprotein E (amyloid signatures), for which its presence in samples serves as an internal control of procedure and confirms amyloid deposits." (PMID 36293523, 2022). "The potential of this APOE/APOA-I mimetic in AD was tested in a mouse model of AD, and was demonstrated to improve cognition, decrease amyloid plaque deposition, and reduce glial activation." (PMID 32899606, 2020). "Here we have examined Trem2 effect in an APOE isoform-dependent and amyloid-dependent manner by directly comparing age-matched APP/E3 and APP/E4 mice that are at different stages of amyloid pathology." (PMID 32703241, 2020). "We found a significant positive correlation between MEV and global amyloid burden in 43 AD-MCI and AD-D patients (r=0.415, P=0.008 after adjustment for age and APOE ɛ4)." (PMID 26151923, 2015). "Greater levels of PA also may reduce the likelihood of amyloid deposition in APOE-ε4 allele carriers more so than in non-carriers, and may promote the activation of semantic memory-related neural circuits to a greater extent in those at increased genetic risk for AD." (PMID 24961307, 2013). "APOE and VTN are generally not regarded as causative amyloidogenic proteins, and consequently, there is no recognized APOE or VTN amyloidosis as defined by the latest classification of the ISA." (PMID 40701201, 2025). "Our findings collectively open new avenues for research into the proteome alterations in amyloid diseases and elucidation of several key proteins that have the potential to be leveraged as biomarkers for V30M ATTRv-PN, including TTR itself, CP, APOE, and the complement pathway proteins such as C3." (PMID 40564999, 2025). "The SCD and MCI cohorts further differed from ADNI CNs in terms of cognitive performance (ADNI MCI and DELCODE MCI), years of education (ADNI SCD and DELCODE MCI), amyloid status (DELCODE SCD and ADNI MCI), and APOE-ε4 carriership distribution (ADNI MCI and DELCODE MCI)." (PMID 38050112, 2024). "We observed a significant reduction in Aβ load in APOE/APP/PS1 mice during a relatively short intervention period, highlighting the potential potency and relevance of humanin P3S in APOE4 biology prior to onset of amyloidosis." (PMID 38520065, 2024). "Downregulating APOE expression overlaps partially with both APOE4 and APOE2 effects, and APOE2 does not counteract APOE4 in amyloid pathology in the early disease stages." (PMID 39528861, 2024). "In our model, we have presented non-cell autonomous effect of different astrocyte-specific APOE isoforms on microglial response to amyloid pathology." (PMID 39528861, 2024). "Higher levels of amyloid accumulation were observed in SCD subjects with ApoE ε4 carriers than noncarriers." (PMID 35530047, 2022).
amyloid (continued). "No changes in brain amyloid load were observed in ApoE carriers, while ApoE non-carriers depicted a decrease in brain amyloid load." (PMID 35015251, 2022). "Area under receiver operating curve (AUROC) analysis of amyloid accompanying proteins (AAPs, including apolipoprotein A-IV, apolipoprotein E and serum amyloid P-component) for discriminating amyloidosis from non-amyloid nephropathies was performed." (PMID 35418036, 2022). "The astrocytic overexpression of apoE4, but not apoE3, suppressed Aβ clearance and also promoted amyloid deposition in cell-type-specific and apoE inducible mouse model." (PMID 34454574, 2021). "As LPS treatment induces acute immune responses, which does not capture the AD-related conditions, future studies on APOE isoform-specific role in innate immunity should be carried out with AD mouse models bearing amyloid and/or tau pathology." (PMID 33148290, 2020). "Reduced amyloid deposition and improved Aβ clearance have been observed in an AD mouse model after overexpressing ABCA1 transporter, whereas deletion of the ABCA1 gene decreases levels of apoE protein and increases the deposition of Aβ." (PMID 32882843, 2020). "INS, IL6 increases while APOE and APOA1 decrease the prediction of amyloidosis." (PMID 32753925, 2020). "Abnormal functional connectivity of the precuneus has also been reported in CN persons with elevated levels of amyloid, as well as CN APOE ε4 carriers without preclinical amyloid deposition." (PMID 31854490, 2020). "Sporadic type of AD that is related to APOE ε4 carrier status does not seem to have any regional predilection for amyloid burden; however, the amyloid deposition tends to have an earlier appearance in ApoE epsilon 4 carriers than non-carriers." (PMID 31242587, 2019). "Still, the lack of APOE neither prevented the recruitment of Aβ at the synapse and nor the decreased synaptic volume characteristic of amyloidosis mouse models." (PMID 30760557, 2019). "By contrast, APOE also appears as an important factor to preserve brain function during aging, even in the absence of amyloid deposition." (PMID 30760557, 2019). "There was no significant amyloid × APOE interaction on inferior temporal or posterior cingulate cortex tau deposition and no amyloid × sex or amyloid × education interaction on any of the 3 regional tau measures." (PMID 31642932, 2019). "To evaluate how the “rescue effect” observed in mice lacking APOE correlated with the level of amyloid pathology, we performed a stereological analysis of the load and density of amyloid plaques in the cortex of APP/PSEN1 and APP/PSEN1/APOEnull mice." (PMID 30760557, 2019). "The phagocytosis of Aβ by astrocytes requires the participation of APOE because APOE null astrocytes are not efficient at amyloid plaque removal." (PMID 29922147, 2018). "The finding that amyloid deposition is more extensive in APOE-4 carriers’ cerebral blood vessels than those of non-carriers supports that theory." (PMID 28376794, 2017). "To study amyloid plaque pathologies induced by TBI, we may need to utilize ApoE mice with an AD transgenic background." (PMID 28900205, 2017). "The advantage is the ability to test any dependence of amyloid deposition and ApoE on functional network properties, solely based on non-invasive and resting-state EEG recordings." (PMID 29081745, 2017). "One interpretation of this is that the primary effect of APOE ε4 is to increase amyloidosis, not to enhance tau deposition, neurodegeneration, or both through non-amyloid related mechanisms." (PMID 28456479, 2017). "The data suggests that the LXR agonist GW3965 is associated with increased expression of ApoE and ABCA1 in the hippocampus and cerebral cortex without a detectable reduction of the amyloid load." (PMID 26720273, 2015).
amyloid (continued). "Cortical amyloid deposition and CSF levels of Aβ were significantly associated with APOE ε4 status but not E-MCI diagnosis, with ε4 positive participants showing more amyloid deposition and lower levels of CSF Aβ than ε4 negative participants." (PMID 23554593, 2013). "We also introduced apoE itself into the circulation via parabiosis and found that it induced amyloid clearance without entering the brain in AD model mice." (PMID 22844635, 2012). "HAE-4, an antibody which preferentially binds non-lipidated, aggregated forms of ApoE, was shown to reduce existing amyloid pathology in the brain parenchyma and cerebral vessels of 5xFAD mice, and to improve cerebrovascular functions as well as suppress Aβ-mediated tau propagation." (PMID 40770764, 2025). "Furthermore, we found that Aβ3pE-40/42, but not Aβ1-40/42, colocalized well with apolipoprotein E (ApoE), which is known to be involved in Aβ aggregation, in the cores of amyloid plaques." (PMID 39348937, 2024). "Notably, the AD‐related network alterations were independent of amyloid pathology and APOE ɛ4 status, and distinct from aging‐related functional network alternations that usually spare sensory‐motor systems relative to association systems." (PMID 38274411, 2024). "Third, we did not match other potential confounders, such as the APOE genotype or various lifestyle factors, both of which could influence brain amyloid deposition, volume, and advanced clinical stages." (PMID 38698190, 2024). "Moreover, ApoE4 enhanced endosomal dysfunction by decreasing the amount of the Na+/H+ exchanger NHE6 and lowering pH in endosomes where ApoE-bound Aβ and its receptor LRP1 remain trapped, resulting in decreased amyloid clearance." (PMID 37705117, 2023). "Several strategies including APOE immunotherapy, antisense oligonucleotides, and APOE-mimetic peptides among others have shown preclinical promise for the treatment of amyloidosis without overt adverse effects on the cerebrovasculature or peripheral lipid homeostasis." (PMID 36922879, 2023). "To assess the effect of ApoE on ADan deposition in an in vivo model of amyloidosis, we generated mice in which the Danish mutant form of human BRI2 is expressed under the control of the mouse prion protein promoter (Tg-FDD) on an ApoE KO (ApoE−/−) background (Tg-FDD+/−/ApoE−/−)." (PMID 36436561, 2022). "Interestingly, the results for prediction of amyloid deposition by PRS follows a different pattern; APOE alone significantly predicted amyloid deposition with AUCAPOE = 76%, and PRS did not improve the prediction accuracy further." (PMID 31199530, 2019). "In supplemental analyses, we observed an association between SNAP groups defined using CSF tau levels and PGRS for AD, suggesting that while APOE does not appear related to SNAP, some of the genetic risk associated with clinical AD is relevant to tau even in the absence of amyloidosis." (PMID 29190651, 2017). "Based on the fact that affected patients with amyloidosis also displayed hypotriglyceridemia and increased plasma levels of HDL-C as compared with non-carriers in the family, we next screened several candidate genes including the APOC3, APOC1, APOC2, APOC4, APOA4, APOA5 and APOE genes." (PMID 26790392, 2016). "This study gives the insight that lower levels of ApoE could have major implications in contributing to the progression of AD as also observed by its negative correlation with neocortical amyloid burden as measured by PiB-PET." (PMID 25859282, 2015). "In addition, apolipoprotein E (APOE) variations may affect cholesterol transport and affect amyloidosis." (PMID 26018424, 2015).